TNF (tumor necrosis factor)
Diseases named in the same sentence as TNF in open-access papers (continued):
Sharing a sentence is not in itself a finding about the gene and the disease.
tumor (continued). "Cytokines, such as tumor necrosis α (TNF-α), interleukin 1β (IL-1β), and interleukin 6 (IL-6), are also shown to correlate with tumor-promoting inflammation." (PMID 31380247, 2019). "The consequences for the tumor resulting from TNF-induced killing of these cell types are, however, complex and yet not predictable." (PMID 31406107, 2019). "This phenomenon was associated with increased production of TNF, IL-6, CSF-1, VEGF-A, and IL-8 by tumor cells, which contribute to the recruitment of macrophages and the polarization of M2-like macrophages." (PMID 31775797, 2019). "Targeting TNFα to tumour ECM has some major benefits: first, the amount of ECM components is high relative to binding moieties in blood vessels or tumour cells, making the targeting particularly effective." (PMID 31709774, 2019). "by gavage reconstituted or attenuated TNF-dependent tumor response to immunotherapy in antibiotic-treated mice, respectively." (PMID 30887236, 2019). "It is well known that PD-L1, on tumor and stromal cells, suppresses the antitumor activity of the immune system through stabilization of TNF-α." (PMID 31013961, 2019). "In terms of the limitations of this work, we cannot demonstrate by which mechanisms TNF-α acts on the progression of the tumour and the consequent increase in the mortality of these patients." (PMID 31870104, 2019). "In contrast to high doses of TNF-α, which are related to tumor destruction, exposure to low doses of this molecule are related to tumor promotion." (PMID 30642137, 2019). "TNF-α is an anti-cancer agent shown to suppress tumor cell proliferation, induce tumor regression, and used as an adjuvant that enhances the anti-cancer effect of chemotherapeutic agents." (PMID 30833944, 2019). "Despite the availability of evidence confirming butein effectiveness in tumor suppression, there is meager research information regarding its influence on the tumor cell response to proinflammatory cytokines, specifically TNF-α." (PMID 31665136, 2019). "CD4+CD8αα and CD4+CD8αβ T cell clones were then stimulated for 48 h with anti-CD3/CD28 antibodies and supernatants were harvested to measure levels of antitumor Th1-type cytokines (IFN-γ, TNF-α), as well as of pro-tumor Th2-type cytokines (IL-4, IL-5)." (PMID 30984190, 2019). "The expression of the tumor suppressive miR-7 in human gastric cancer inversely correlates with the levels of IL-1β and TNFα, suggesting that miR-7 down-regulation is related to the severity of inflammation and contributes to gastric tumorigenesis." (PMID 31557902, 2019). "Complementary to their cytotoxic activity, Trm cells secrete large amounts of effector molecules, most prominently IFN-γ and TNF-α, which can activate other immune cells with anti-tumor potential." (PMID 31562311, 2019). "TNF has anticancer and anti-infection effects in high concentrations because of its cytotoxic effects on the tumor vessel." (PMID 31341911, 2019). "TNFα produced in the setting of anti-PD-1 blockage leads to impaired CD8+ tumor infiltrating T lymphocyte responses." (PMID 31439050, 2019). "Activation of oncogenic signaling pathways in epithelial cells, including Wnt and NF-κB, is critical for TNF-α-induced tumor growth." (PMID 30642137, 2019). "CAFs that were activated by tumor-derived pro-inflammatory signaling (TNFα and IL-1β) secreted TSLP, which endowed them with the ability to drive the differentiation of naïve CD4+CD45RA+ T cells toward a Th2 phenotype." (PMID 31428105, 2019). "In this study, we verify TNF-α as a crucial pro-inflammatory factor within GC microenvironment, which derived from GC tumor and effectively induces the expression of PD-L1 on mast cells via activation of NF-κB signaling pathway." (PMID 30808413, 2019). "TNFR1 mediates TNF-α-induced tumor lymphangiogenesis and metastasis by modulating VEGF-C-VEGFR3 signaling." (PMID 30847024, 2019).
tumor (continued). "TNF is a pro-inflammatory cytokine with known tumor promoting and tumor repressing properties studied in many types of cancers, including lung, and is involved in both acute and chronic inflammation." (PMID 31018556, 2019). "TNF-α is likely to need the synergistic activities of additional tumor-derived factors or cytokines to develop sarcopenia." (PMID 30754663, 2019). "Functional analyses showed that MAIT cells freshly isolated from healthy donors produced less IFN-γ and TNF-α when activated in the presence of tumor conditioned media prepared from stage III OAC tumors." (PMID 31354725, 2019). "The inflammatory cytokine TNF-α is involved in the pathogenesis of septic shock, while NO production plays an important role in killing microbes, parasites, and tumor cells." (PMID 31744147, 2019). "Co-culture of murine bone marrow cells with tumor culture conditioning medium caused increased production of both, VEGF and TNF." (PMID 30374596, 2019). "Similar to TAMs, it is likely that MDSCs are stimulated by a variety of soluble factors, such as GM-CSF, VEGF, TNF-α, PGE2, IL-1β, IL-6, and IL-10, which are secreted by tumor and infiltrating immune cells, as well as tumor-associated fibroblasts." (PMID 31428574, 2019). "Now, in the presence of TNFα-induced signals, activation of p65 in the tumor cells has contributed much to CXCL8 release, and p65 activation in the MSCs provided its share as well." (PMID 31105691, 2019). "GDF-15 reduces TNFα synthesis, and is followed by reduced TNFα-dependent tumor cell apoptosis and enhanced tumor growth." (PMID 30764482, 2019). "Apoptosis can also be induced in tumor cells by inhibiting their growth with tumor necrosis factor (TNF), which binds to the appropriate receptor on the surface of cancer cells and causes their elimination." (PMID 31546724, 2019). "And then, tumor-derived TNF-α induces the overexpression of PD-L1 on mast cells via NF-κB signaling pathway activation." (PMID 30808413, 2019). "CD11b+ Ly6G+ neutrophils isolated from bone marrow of normal mice or spleen of tumor-bearing mice inhibited T cell proliferation in vitro after coculture with TNF-α-primed MSC with and enhanced 4T1 tumor progression in vivo." (PMID 31379875, 2019). "CD163-targeted crosolic acid-containing liposomes prevent the expression of STAT3 in macrophages, resulting in enhanced anti-tumor immunity by increasing TNF-α, IFN-γ, IL-12 and IL-2 levels, and decreasing the IL-10 level." (PMID 31569687, 2019). "Growing evidence has demonstrated that TNF-α participates in several key processes of tumor progression, including oncogene activation, DNA damage, and tumor metastasis." (PMID 30600678, 2019). "TNF damages the tumor endothelium leading to a rapid hemorrhagic necrosis of the neoplastic mass, while IL2 mainly acts by activating NK cells and CD8+ lymphocytes." (PMID 31799191, 2019). "TNF-α expression was measured in lysates prepared from the right brain cortex that contained the VM-M3 tumour." (PMID 31149644, 2019). "This phenomenon triggers the expression of multiple cytokines including TNFα from tumor-infiltrating macrophages exposed to OC cells." (PMID 31443240, 2019). "UPR is also involved in tumor development and progression by promoting the expression of tumor growth factors such as TNF-α, IL-8, and VEGF5,6." (PMID 31320625, 2019). "TNF-α is a major mediator of inflammation in the tumor microenvironment during early tumorigenesis, controlling a cascade of cytokines, chemokines, adhesion molecules, and pro-angiogenic activities." (PMID 31656195, 2019). "In tumor tissue, the number of FoxP3+ Tregs was positively correlated with IL-6 expression and negatively correlated with IL-2 and TNF-α expression (R2 = 0.0720, P = 0.0161; R2 = 0.1030, P = 0.0037; and R2 = 0.0507, P = 0.0446, respectively)." (PMID 31417548, 2019). "Cytokines, such as IFN-γ and TNF-α, can promote the expression of HLA I and increase the expression of peptide/HLA I on the surface of tumor cells." (PMID 31408937, 2019).
tumor (continued). "Tumor-released cytokines, such as TNF-α or IL-1, are involved in the NF-κB and MAPK pathways to lead to breakdown of structural muscle proteins and inhibition of protein synthesis." (PMID 31781219, 2019). "Neo-epitope-specific CD8+ T cells displayed high expression of other effector molecules, such as TNF-α, granzyme B and IL-2, which is consistent with anti-tumor cytotoxic activity." (PMID 31562311, 2019). "An increased generation of effector interferon (IFN) ɣ and TNFα-producing CD8+ T cells was observed in tumor-infiltrating lymphocytes in bone marrow chimeras bearing ATG5-deficient donor cells, which led to improved tumor control." (PMID 31632966, 2019). "In particular, several pro-inflammatory cytokines such as TNF-α, IL-1β, and IL-6 produced by ovarian tumor cells or activated immune cells, have been shown to increase tumor growth and influence clinical disease outcome and prognosis." (PMID 31320999, 2019). "Either Sal-B or cisplatin treatment decreased tumor tissue levels of tumor necrosis factor (TNF-α), matrix metalloproteinase-8 (MMP-8), and Cyclin D1 in ESC treated mice." (PMID 31726654, 2019). "TNF-α is able to alter endothelial barrier function and tumor interstitial pressure to enhance the penetration of chemotherapeutic drug." (PMID 31171917, 2019). "IL-1β activates endothelial cells to produce vascular endothelial growth factor (VEGF) and other proangiogenic factors (e.g., TNF) which provide an inflammatory microenvironment for angiogenesis and tumor progression." (PMID 30642137, 2019). "On the one hand, it is connected to tumor promotion by stimulating survival, proliferation, migration, and angiogenesis in most cancer cells that are resistant to TNF-induced cytotoxicity." (PMID 31861498, 2019). "It is accepted that UPR signaling is important for generating malignancy through induction of tumor-promoting factors such as TNF-α, IL-8, and VEGF5,6." (PMID 31320625, 2019). "Colon inflammation contributes to colorectal cancer development, by modulating the expression in tumor lesions of cytokines such as TNFα and IL6 and chemokines, i.e., CXCL1, prostaglandins, COX-2, and Wnt5A (Wnt Family Member 5A)." (PMID 31799175, 2019). "Genes linked to both anti-viral and anti-tumor immune effector responses such as toll-like receptor 8 (TLR8), tumor necrosis factor (TNF), and interferon γ (IFN γ) were upregulated after MeVac FmIL-12 treatment." (PMID 31623390, 2019). "Activation of macrophages enhanced the production of TNF-α and IL-12 after two days of co-culture with tumor cells as detected by ELISA assay, while ARG1 remained unchanged among all panels except for the 3 min plasma-exposed macrophages." (PMID 31216715, 2019). "The TNF-α-induced self-renewal phenotype was further investigated by tumor sphere formation assay to make evident the ability of TNF-α in promoting the self-renewal of HCC cells." (PMID 31650028, 2019). "The mRNA expression levels of COX2, TNF-α, Il-6, and Ccl2 were significantly decreased in the tumor tissues of the Ct55 knockout mice compared with those of the WT mice." (PMID 30944312, 2019). "Tumor necrosis factor (TNF) was first described in the early 1960s as its originally discovered role during tumor regression in rodents." (PMID 31877663, 2019). "For example, in resveratrol-treated mice the reduction in tumor size correlated with miR-101b and miR-455 upregulation, which in turn led to the downregulation of the target cytokines IL-6 and TNF-alpha." (PMID 30959836, 2019). "The results demonstrated that PRO, PRE, and PRO-PRE combination are significantly able to suppress the tumor frequency, raise the TCD4+ in tumor tissue, and decrease the serum level of TNFα." (PMID 31771178, 2019). "In general, M1 macrophages facilitate tumor regression and Th1 responses by secreting tumor necrosis factor-α (TNF-α) and IL-12; on the other hand, M2 macrophages display an immune suppressive phenotype and release IL-10 which promotes a Th2 response." (PMID 30987642, 2019).
tumor (continued). "TNF-α contributes to breast cancer metastasis through the recruitment of tumor-infiltrating macrophages, neutrophils, and T cells, leading to immune evasion, tumor growth, and metastasis." (PMID 30764536, 2019). "Administration orally mice with crocetin in methylcholanthrene (MCA)-induced rodent tumor model showed the anti-inflammatory effect via downregulating IL-1β, TNF-α and polymorphonuclear cells (PMN)." (PMID 31223464, 2019). "More importantly, the adoptive transfer of TNF-α-treated Th9 cells induces more potent antitumor effects than regular Th9 cells in mouse tumor models." (PMID 30717817, 2019). "Functional prediction revealed that 8 lncRNAs have potential effects on tumor immune processes such as lymphocyte activation and TNF production in NSCLC." (PMID 30659574, 2019). "We found that both TNF-α and Tim-3 were highly expressed in tumor tissues compared to adjacent tissues." (PMID 31109341, 2019). "High levels of tumor necrosis factor-α can lead to systemic and immune dysfunction through multiple pathways, thereby promoting tumor cell invasion and metastasis." (PMID 30651572, 2019). "TNF-α is a cytokine with a molecular weight of 26 kDa and it regulates different mechanisms (e.g., immunity, inflammation, cellular homeostasis, and tumor progression), according to its concentration." (PMID 31191652, 2019). "For instance, TNF-α has been shown to have cytotoxic activity in tumor cells in paraformaldehyde-fixed activated monocytes." (PMID 30600678, 2019). "Increased tumor incidences in Brg1IEC-AKO mice were associated with the persistent inflammation, as reflected by increased IL-6, IL-1β, TNFα and CCL2 productions in the 5 months of AOM-treated Brg1IEC-AKO mice." (PMID 31601814, 2019). "The morphology of the tumor cells under this condition was robustly different from the morphology of tumor cells grown alone, of tumor cells stimulated by TNFα and of tumor cells grown with MSCs only (Figure 9A1)." (PMID 31031757, 2019). "Depletion of FAP+ CAFs using transgenic mice with FAP promoter- driven diphtheria toxin receptor (DTR) resulted in tumor regression in an IFNγ and TNFα dependent manner." (PMID 31428105, 2019). "A similar pattern of gene expression was observed in neutrophil TNFα with the difference that at the 14th day the TNFα expression values were the same as the first 12 h after tumor inoculation." (PMID 31712726, 2019). "AVA treatment significantly decreased TNF-α levels in tumor sections, confirming the scavenger activity of AVAs, widely described in vitro." (PMID 31540249, 2019). "TNF-α is produced mainly by macrophages, granulocytes and epithelial cells but also by other types of cells and its anti-tumor properties are due to direct cytotoxic and antiangiogenic effects." (PMID 31179236, 2019). "Prospective data will be necessary, however, to clearly define populations where anti-TNFα concurrent with immunotherapy is both safe, and leads to improved tumor outcomes." (PMID 31439050, 2019). "Macrophage polarization was simulated to occur in the tumor microenvironment based on the levels of cytokines present therein, with TNF-α and TGFβ1 being representative molecules influencing M121 and M222 polarization, respectively." (PMID 31636296, 2019). "Th1 cells, identified by their expression of IFN-γ and TNF-α, were reduced both in frequencies and numbers in the tumor mass of BATF3-/- mice." (PMID 31188899, 2019). "In terms of tumor inhibition, IEXs exert anti-tumor response primarily through their contents, such as TNF-α, perforin, FasL and so forth." (PMID 31647023, 2019). "Intravenously injected TNFα‐CSG triggered robust immune cell infiltration in mouse tumours, particularly in the ECM‐rich zones." (PMID 31709774, 2019). "Pro-inflammatory cytokines, such as TNFα and IL-6 secreted in the tumor microenvironment by immune cells or tumor cells, can drive tumor plasticity and increase cancer stem cell maintenance, as observed in numerous malignancies including GBM2." (PMID 30854231, 2019).
tumor (continued). "A study in a model of inflammation-associated cancer revealed that TNFR2 is preferentially upregulated over TNFR1 and that treatment with the anti-TNF monoclonal antibody reduced the number and size of tumours." (PMID 31239840, 2019). "TNF has a ubiquitous influence on different cells and tissues and has an important role in the tumour microenvironment." (PMID 30755793, 2019). "Another factor that regulates the TME is TNF-α, a pleotropic cytokine that plays a key role in the regulation of apoptosis, tumor angiogenesis, inflammation, and immunity." (PMID 31861801, 2019). "Increased NF-κB signaling in CD4+ T cells has been linked with increased anti-tumor response by increased secretion of granzyme B, TNF-α (tumor necrosis factor alpha), and interferon-γ." (PMID 31394796, 2019). "In this context, TNFα, produced by the tumor cells themselves and by tumor-infiltrating inflammatory cells, is involved in carcinogenesis, tumor progression, metastases, and anti-cancer immune control." (PMID 30764482, 2019). "M2 macrophages are involved in the enhancement of immunosuppression through the stimulation of Tregs and the secretion of TGF-b, TNF-a, and IL-10, leading to the creation of a favorable tumor microenvironment." (PMID 31510065, 2019). "Various pro-inflammatory mediators that have been demonstrated to change the tumor microenvironment, including members of tumor necrosis factor (TNF)-superfamily, are modulated by NF-kB." (PMID 31341423, 2019). "For example, soluble factors secreted by tumor cells such as TNF-α, promote Bregs differentiation and enhances their activity." (PMID 31737559, 2019). "This study established a new field of application for the licensed anti-tumor drug epirubicin as an anti-inflammatory agent, reducing IL-1β and TNF-α release from macrophages when used at low-doses." (PMID 31905600, 2019). "Here, we identified serum amyloid A (SAA) for proinflammatory predisposition in BC through the signature profiles of APPs, interleukin (IL) and tumor necrosis factor (TNF) superfamily using publicly available datasets of tumor samples and cell lines." (PMID 30728901, 2019). "Interleukin-6 (IL-6) and tumor necrosis factor-alpha (TNFα), which are involved in tumor-related inflammatory processes, are known to induce neutrophilia independently." (PMID 30917620, 2019). "After activation, NK cells can secrete IFN-γ, TNF-α, and granulocyte macrophage-colony-stimulating factor (GM-CSF) to exert anti-tumor effects." (PMID 30646912, 2019). "If miR-21 expression is suppressed by TNF-α, therapeutic use of Infliximab would increase miR-21, which would promote tumor progression." (PMID 30999696, 2019). "One study demonstrated that TNF-α secreted by tumor cells stimulated the growth of malignant mammary epithelial cells, which contributed to mammary tumorigenesis in neu/erbB2 transgenic mice." (PMID 31341911, 2019). "In turn, TNF-α can facilitate tumor cell apoptosis and macrophage and dendritic cell infiltration into the local tumor, suggesting direct and indirect antitumor immune responses." (PMID 31781671, 2019). "More recent evidence suggest that TNF can bind to TNF receptor 2 (TNFR2) expressed predominately on regulatory T-cells (Tregs) to suppress anti-tumor immunity." (PMID 31174326, 2019). "Combined, our results describe a mechanism by which autocrine TNFα signaling, induced by cGAS/STING signaling upon loss of the BRCA2 tumor-suppressor gene, limits tumor cell viability." (PMID 30626869, 2019). "Sal-B or cisplatin treatment significantly reduced the tumor tissue level of the inflammatory cytokine TNF-α in ESC injected mice." (PMID 31726654, 2019). "The NF-κB signaling pathway induces the production of cytokines that regulate the immune response (e.g., TNFα, IL-1, IL-6, and IL-8) as well as adhesion molecules that lead to the recruitment of leukocytes into tumor sites." (PMID 31775797, 2019).